OLIG1 (oligodendrocyte transcription factor 1)
Description:
Orchestrates progenitor cell fates during cortical gliogenesis and gliomagenesis. In cooperation with OLIG2, activates oligodendrocyte precursor cells (OPCs) formation while repressing the generation of olfactory bulb interneuron intermediate progenitors (OBIN) through transcriptional regulation of GSX2. Mechanistically, binds and silences multiple conserved enhancer elements of GSX2. Cooperates with OLIG2 to establish the pMN domain of the embryonic neural tube (By similarity).
Synonyms: bHLHb6; bHLHe21
Tractability: No criterion of Open Targets' tractability assessment is met for any kind of drug.
Gene: Protein-coding gene on chromosome 21 (33,070,141 to 33,072,413, forward strand). Ensembl gene ENSG00000184221.
Subcellular location: Nucleus
Gene Ontology:
Molecular function: protein binding; DNA-binding transcription factor activity, RNA polymerase II-specific; E-box binding; protein dimerization activity
Biological process: axon development; positive regulation of transcription by RNA polymerase II; sensory organ development; oligodendrocyte development
Cellular component: chromatin; nucleus
Genetic constraint (gnomAD): Loss-of-function variants: 9 observed, 6.3 expected, observed/expected ratio (o/e) 1.43, 90% interval 0.83 to 1.92. That is too few expected variants to judge how well the gene tolerates losing a copy. Missense variants: 362 observed, 246.82 expected, observed/expected ratio (o/e) 1.47, 90% interval 1.35 to 1.6. Synonymous variants: 215 observed, 134.14 expected, observed/expected ratio (o/e) 1.6, 90% interval 1.43 to 1.79.
Homologues: Orthologues: chimpanzee OLIG1 (99% identical), dog OLIG1 (92% identical), pig OLIG1 (92% identical), rabbit OLIG1 (89% identical), rat Olig1 (87% identical), mouse Olig1 (86% identical), guinea pig OLIG1 (84% identical), zebrafish olig1 (35% identical), Caenorhabditis elegans ngn-1 (14% identical), Drosophila melanogaster tap (13% identical), Caenorhabditis elegans lin-32 (13% identical), Drosophila melanogaster ato (13% identical), and 1 more. Paralogues in human: OLIG3 (31% identical), OLIG2 (30% identical), BHLHE22 (25% identical), BHLHE23 (24% identical), NEUROD2 (19% identical), NEUROG2 (18% identical), NEUROD1 (18% identical), NEUROD4 (18% identical), ATOH1 (16% identical), NEUROD6 (16% identical), NEUROG1 (15% identical), NEUROG3 (14% identical), and 3 more.
Diseases named in the same sentence as OLIG1 in open-access papers:
OLIG1 is named in the same sentence as 49 diseases in open-access papers, as found by Europe PMC text mining. Sharing a sentence is not in itself a finding about the gene and the disease. The quoted sentences say what the papers report.
glioma (15 papers, 2005 to 2025). A benign or malignant brain and spinal cord tumor that arises from glial cells (astrocytes, oligodendrocytes, ependymal cells). "Hypermethylated regions specific to G34R-mutated gliomas were enriched for CGIs, including those of OLIG1, OLIG2, and canonical histone genes in the HIST1 cluster." (PMID 32999376, 2020). "Both Olig1 and Olig2 are ubiquitously expressed in gliomas and play pivotal roles in tumorigenesis and phenotypic plasticity." (PMID 40428395, 2025). "While Olig2 has been extensively studied in proneural GBM subtypes for its role in maintaining glioma stem cells (GSCs), our work highlights the cooperative function of Olig1/2 in astrocytic-featured GBM." (PMID 40428395, 2025). "According to scRNA-seq and qPCR-RT data, rat glioma 101.8 tumor cells are characterized by high expression levels of the oligodendroglial markers Olig1 and Olig2." (PMID 41009560, 2025). "We analyzed these cells for the expression of neural/stem precursor cell markers (OLIG1, OLIG2, CSPG4/NG2, NESTIN), which are also transcription factors and lineage markers associated with glioma stem cells (GSC), and DMRTA2." (PMID 38509074, 2024). "The presence of astrocyte-like SOX9+ and oligodendrocyte-like OLIG1+ cells in grade II IDH1-mutant gliomas raises new questions about their role in the pathology." (PMID 33925547, 2021). "By coupling CRISPR/Cas9-mediated double knockout with lineage tracing, we found that the loss of Olig1/2 does not alter glioma characteristics but inhibits tumor proliferation." (PMID 40428395, 2025). "By co-opting chromatin-modifying complexes to activate cyclin-driven cell cycle programs, Olig1/2 may license neural precursor-like proliferative states in glioma stem cells—a potential vulnerability for targeted therapies." (PMID 40428395, 2025). "OLIG1 and other oligodendrocyte markers were highly expressed in OLIG1 + malignant cells, which may be oligodendrocyte progenitor glioma mother cells." (PMID 36647156, 2023). "Interestingly, we found that a subset of TAMs also express genes encoding the markers of glioma cells, such as GFAP, DLL3, OLIG1 and SOX4." (PMID 34805184, 2021). "Therefore, the expression of survival-associated genes in ODG and OAC can be divided into at least two subgroups; genes such as Olig1 and Olig2 that are expressed in all glial tumors, and genes such as Fabp7 that are restricted to astrocytes." (PMID 16018821, 2005). "The fact that Olig1 and Sox4 mRNA levels were reduced in MNF-treated C6 glioma tumors compared with the control group is consistent with decreased activation of molecular pathways leading to gliomagenesis." (PMID 25505565, 2013). "More recent work, however, has demonstrated that OLIG1 and OLIG2 are expressed in all glioma subtypes including astrocytoma, ODG, and OAC." (PMID 16018821, 2005). "Hence, rat glioma 101.8 is potentially a quite reliable preclinical model to evaluate the anti-tumor efficacy of SOX2-, OLIG1/2-, and PDGFRA-targeting therapy approaches." (PMID 41009560, 2025). "Although previous studies suggested glioma expression of oligodendrocyte progenitor cell antigen NG2 and PDGFRα, and transcription factor Olig1/2, the lineage commitment and the stage of differentiation blockage of glioma cells are not clarified." (PMID 18398462, 2008). "Based on the function of Id4, OLIG1, and OLIG2 during normal development, our data suggest that Id4 and potentially other genes such as Fabp7 and Ptprz1 might account for the formation of distinct glioma subtypes during oncogenic progression." (PMID 16018821, 2005). "The functions of Id4, OLIG1, and OLIG2 during normal development, and our data suggest that Id4 and potentially other proteins such as FABP7 and PTPRZ1 might account for the formation of distinct glioma subtypes during oncogenic progression." (PMID 16018821, 2005).
schizophrenia (7 papers, 2007 to 2025). A major psychotic disorder characterized by abnormalities in the perception or expression of reality. "About half of them has been previously associated with schizophrenia in humans, such as Olig1, Fgfr1, Gpr17, Gna12, Abca2, Sox1, Dpm2, and, as a locus for de novo mutations, Rab2a." (PMID 39825014, 2025). "As a regulator of Olig2, Olig1 could be considered as another candidate gene for the susceptibility to schizophrenia." (PMID 18021424, 2007). "An RNA sequencing analysis of the PFC suggested a dysregulation of numerous schizophrenia related genes including Olig1, Fgfr1, Gpr17, Gna12, Abca2, Sox1, Dpm2, and Rab2a in the rat model of psychosis." (PMID 39825014, 2025). "Here, we did find a trend towards a reduction of Olig1-stained cells in CA4, which points in the same direction as the decrease of oligodendrocyte number in this area in schizophrenia found in our previous stereological studies." (PMID 27065804, 2016). "Moreover, the downregulation of myelin-related and oligodendrocyte genes such as proteolipid protein 1 (PLP1), transferrin (TF), oligodendrocyte transcription factor 1 (OLIG1), and upregulation of myelin basic protein (MBP) were reported in the PFC of patients with schizophrenia." (PMID 36833173, 2023).
glioblastoma (5 papers, 2013 to 2025). The most malignant astrocytic tumor (WHO grade IV). "In the past several years, the oligodendrocyte transcription factor 1 (Olig1) has been identified as a novel glioblastoma marker with diagnostic and prognostic value." (PMID 25505565, 2013). "At the same time, Olig1/2+ cells also occurred in glioblastoma, including low-differentiated cells, which led to aggressive tumor growth and a negative prognosis for patients." (PMID 41009560, 2025). "However, MGH57 (grade IV glioblastoma) revealed a relatively small subpopulation of malignant cells that do not express OLIG1, OLIG2, DLL1, CCND1, and IGFBPL1, but express ALDOC and ATP1A2." (PMID 33607293, 2021).
multiple sclerosis (5 papers, 2010 to 2024). A progressive autoimmune disorder affecting the central nervous system resulting in demyelination. "In a similar study, it was also shown that progesterone upregulates the expression of MBP, PLP, Nkx 2.2, and Olig1 in the spinal cord of a murine model of multiple sclerosis." (PMID 32295179, 2020). "Furthermore, an association between OLIG1 expression and certain disorders of the central nervous system, e.g., the repair of myelin in multiple sclerosis, was previously reported; however, it is still unknown whether OLIG1 is associated with PVL in premature infants." (PMID 25435330, 2015). "Here we investigated the effects of Olig1 deficiency on experimental autoimmune encephalomyelitis (EAE), an animal model of multiple sclerosis (MS)." (PMID 20927333, 2010). "Additionally, in multiple sclerosis, the repair and regeneration of the myelin sheath can be facilitated by the nuclear transcription function of Olig1." (PMID 34569901, 2021).
oligodendroglioma (5 papers, 2015 to 2025). A well-differentiated (WHO grade II), diffusely infiltrating neuroglial tumor, typically located in the cerebral hemispheres. "PDGFRA and SOX8 were clearly more associated with OLIG1+ cells in both the oligodendroglioma and the astrocytoma." (PMID 33925547, 2021). "OLIG1/2 expression was observed mainly in oligodendroglioma of various degrees of malignancy including grades 3–4." (PMID 41009560, 2025). "Surprisingly, we found that these two receptors were more expressed in OLIG1+ cells in the explored oligodendroglioma and astrocytoma." (PMID 33925547, 2021). "On the contrary, ASCL1 and SOX4 expression were clearly more expressed in OLIG1+ cells in both the explored oligodendroglioma and astrocytoma samples." (PMID 33925547, 2021). "In this study, OLIG1 was highly expressed in oligodendrogliomas and considered as biomarker for glial brain tumors." (PMID 26337083, 2015). "For GPR17, its expression was more confined to OLIG1+ cells in the oligodendroglioma, whereas a similar expression was found in the SOX9+ and OLIG1+ subpopulations in the explored astrocytoma." (PMID 33925547, 2021). "Here, we report that SOX9 and OLIG1 transcription factors, which specifically label astrocytes and oligodendrocytes in the normal brain, revealed the presence of two largely nonoverlapping tumoral populations in IDH1-mutant oligodendrogliomas and astrocytomas." (PMID 33925547, 2021).
astrocytoma (4 papers, 2005 to 2025). "Both astrocytomas and oligodendroglial tumors in humans demonstrate diffuse expression of OLIG1 and OLIG2, although expression of OLIG2 is lower and increasingly variable and heterogeneous in GBM as compared to ODG tumors." (PMID 16018821, 2005). "Highexpression of OLIG1 and OLIG2 is also seen in anaplasticoligodendroglioma and astrocytoma." (PMID 31312081, 2019).
Anxiety (2 papers, 2021 to 2023). Intense feelings of nervousness, tension, or panic often arise in response to interpersonal stresses. "Viral overexpression of the oligodendrogenic factor Olig1 in the dentate gyrus was sufficient to induce an anxiety-like behavioral phenotype." (PMID 34903726, 2021). "In addition, overexpression of oligodendrogenic factor Olig1 through viral infection in the dentate gyrus can induce an anxiety-like behavioural phenotype." (PMID 37592237, 2023).
autoimmune disease (2 papers, 2010 to 2024). A disorder resulting from loss of function or tissue destruction of an organ or multiple organs, arising from humoral or cellular immune responses of the individual to their own tissue constituents. "Since EAE is a T cell-mediated autoimmune disease, we first assessed the effect of Olig1 deficiency on T-cell proliferation capability." (PMID 20927333, 2010).
breast carcinoma (2 papers, 2019 to 2021). "Smad cofactors that have been reported to be involved in TGF-β-induced cell motility or invasion include JunB in breast cancer cells, Olig1 in NMuMG cells, and Sox4 in nontransformed human mammary epithelial cells." (PMID 33741342, 2021). "Our results revealed that the simultaneous existence of YB-1 and the other four (SOX2, POU3F2, OCT-4, and OLIG1) or five (SOX2, SALL2, OCT-4, POU3F2, and Bmi-1) transcription factors reverted YB-1-deleted melanoma stem cells or breast cancer stem cells, respectively, into cancer stem cells." (PMID 31375149, 2019).
cognitive deficit (2 papers, 2016 to 2020). "The widespread effect of Olig1 and Olig2, e.g., overexpression from the early developmental stage, was the main component of the cognitive deficit phenotype in DS." (PMID 33329702, 2020).
diffuse midline glioma (2 papers, 2017 to 2021). A diffuse glioma that arises from the midline structures of the central nervous system. "GPR17 clustering is associated with the overexpression of transcription factors such as Olig1 and Olig2 in pediatric diffuse midline glioma (pDMG), with the aborted differentiation of the oligodendrocytic lineage of the cells." (PMID 34359676, 2021).
brain ischemia (1 paper, 2022). Diminished or absent blood supply to the brain caused by obstruction (thrombosis or embolism) of an artery resulting in neurologic damage. "Previous reports have also suggested the potential involvement of OLIG1 in brain ischemia repair mechanisms when observed that its expression pattern was closely associated with endogenous remyelination." (PMID 36405721, 2022).
brain tumor (1 paper, 2019). "The salient features of genes OLIG1, OLIG2 and OLIG3 havingconserved bHLH domain that are associated with brain tumor arediscussed." (PMID 31312081, 2019).
deafness (1 paper, 2023). An inherited or acquired condition characterized by the complete loss of the ability to hear from one or both ears. "Moreover, the inclusion among the DEGs of genes involved in inner ear development and deafness (Atoh1, Edn1, Hes1, Kl, Myc, Mycn and Olig1) suggested their interaction with Dmp1 in these processes." (PMID 37106825, 2023).
demyelinating disease (1 paper, 2010). A broad group of disorders that affect the myelin sheaths that cover the neurons. "Combining these data with our data, one may speculate that downregulation of Olig1 during inflammation and upregulation of Olig1 in the remyelination phase may prove to be one of the useful strategies against demyelinating diseases." (PMID 20927333, 2010).
depression (1 paper, 2024). "Of thirteen depression‐associated DRPs, seven proteins including DDC, FGFR2, KIBRA, MED22, OLIG1, RAI1, SLIT2 were upregulated, whereas six proteins including COX3, CRHBP, CSMD1, FSTL1, GRIK4, and LMTK3 were downregulated." (PMID 39373701, 2024).
Down syndrome (1 paper, 2015). "Olig1 and Olig2 triplication is associated with developmental brain defects in Down syndrome." (PMID 26035870, 2015).
epilepsy (1 paper, 2021). A brain disorder characterized by episodes of abnormally increased neuronal discharge resulting in transient episodes of sensory or motor neurological dysfunction, or psychic dysfunction. "Hence, the epilepsy in CKOOlig1 mice is related to pathological changes in the cortex, especially abnormal Olig1-positive cells." (PMID 33608505, 2021). "In our study, epilepsy was found in FGF9 knockout in Olig1-postive progenitors rather than in Olig2-postive progenitors, which regulates the sequential specification of neural progenitor cells into motor neurons and oligodendrocyte precursor cells." (PMID 33608505, 2021).
experimental autoimmune encephalomyelitis (1 paper, 2010). An autoimmune demyelinating disease of the central nervous system that is produced experimentally in animals by the injection of homogenized brain or spinal cord in Freund's adjuvant. "In the present study, we investigated the effects of Olig1 deficiency on experimental autoimmune encephalomyelitis (EAE), an animal model of MS." (PMID 20927333, 2010).
hypothyroidism (1 paper, 2023). Abnormally low levels of thyroid hormone. "For example, we did not detect a downregulation of genes related to oligodendrocyte progenitors (i.e., Ng2, Olig1, Olig2) in PTU exposed animals, even though reduced myelination is well established consequence of hypothyroidism." (PMID 36843608, 2023).
injury (1 paper, 2015). Damage inflicted on the body as the direct or indirect result of an external force, with or without disruption of structural continuity. "Therefore, the dynamic changes in OLIG1 expression in the presence of HI-induced WMD and the role of OLIG1 in promoting the repair and regeneration of OLs and myelin following PVL brain injury need both to be confirmed by future studies." (PMID 25435330, 2015).
ischemic stroke (1 paper, 2024). A stroke disorder caused by obstruction of blood flow to the brain, due to thrombotic (local blood clot formation) or embolic (due to a blood clot or other material traveling from another site) event. "Although Tbx18-tdT+ cells can generate a small number of Sox2+ i-NSCs following ischemic stroke at both 1 and 3 dpi, they barely produce DCX+ neuroblasts and Olig1+ OL lineage cells." (PMID 39431007, 2024). "Intriguingly, the population of NG2-tdT+/Olig1+ OLs was not altered following both physical and ischemic stroke injuries, at the range of between 6% and 10% of NG2-tdT+ cells." (PMID 39431007, 2024).
leukodystrophy (1 paper, 2024). Leukodystrophies are a group of rare, progressive, metabolic, genetic diseases that affect the brain, spinal cord and often the peripheral nerves. "Together, these results indicate that leukodystrophy-related RNF220 mutations impair its regulation of ubiquitination of Olig1 and Olig2 and their protein stability." (PMID 38324685, 2024).
lung carcinoma (1 paper, 2007). "In particular we were able to show that survival at 60 months, a common clinical parameter for assessing lung cancer prognosis, is significantly associated with OLIG1 protein expression." (PMID 17388669, 2007). "This correlation needs to be tested in a clinical setting to see if adding OLIG1 expression to the current prognostic parameters can lead to better treatment choices for early-stage lung cancer patients and ultimately improve these patients' overall survival." (PMID 17388669, 2007). "Next, the human lung cancer cell lines A549 and H1299, in which OLIG1, BAHD1, and DMRTA1 are methylated and not expressed, were treated with 1 μM of 5-aza-2′-deoxy-cytidine (5-aza-dC) for 48 and 72 h." (PMID 17388669, 2007).
neuromyelitis optica (1 paper, 2010). A rare inflammatory disease of the central nervous system characterized mainly by attacks of uni- or bilateral optic neuritis (ON) and acute myelitis. "As MS often induces visual disturbance, especially in the optic-spinal form of MS or neuromyelitis optica (NMO), we next examined the effect of Olig1 deficiency on the severity of optic neuritis from both the physiological and histopathological aspects." (PMID 20927333, 2010).
neuropathy (1 paper, 2022). A disorder affecting the nervous system that manifests with pain, tingling, numbness, and/or muscle weakness. "Dead M. leprae increased the expression of WNK, IFNB, IKBKA, and HLA-DQA1 (genes related to neuropathy), in addition to GJA1 and RAF1 (for Schwann cell reprogramming) and KCNJ10, OLIG1, SHH, and SOSTDC1 (for neural regeneration)." (PMID 35492305, 2022).